WWOX (WW domain containing oxidoreductase)
Description:
Putative oxidoreductase. Acts as a tumor suppressor and plays a role in apoptosis. Required for normal bone development (By similarity). Plays a role in TGFB1 signaling and TGFB1-mediated cell death. May also play a role in tumor necrosis factor (TNF)-mediated cell death. Inhibits Wnt signaling, probably by sequestering DVL2 in the cytoplasm.
Synonyms: FOR; SDR41C1; WOX1; D16S432E; DEE28; EIEE28; FRA16D; HHCMA56; PRO0128; SCAR12
Tractability: Antibody: its Gene Ontology location is reachable by antibodies, with high confidence. PROTAC: UniProt records ubiquitination sites on it; ubiquitination databases record sites on it; its protein half-life has been measured.
Safety:
Unwanted effects reported when the protein is acted on. In parentheses: how it was acted on, where the effect was seen, and who reports it.
diarrhea (source: ClinPGx)
Gene: Protein-coding gene on chromosome 16 (78,099,400 to 79,212,667, forward strand). Ensembl gene ENSG00000186153.
Subcellular location: Cytoplasm; Nucleus; Mitochondrion; Golgi apparatus; Lysosome
Subcellular location (Human Protein Atlas): Golgi apparatus; Cytosol; Nucleoplasm
Pathways (Reactome):
Gene expression (Transcription): Activation of the TFAP2 (AP-2) family of transcription factors; Negative regulation of activity of TFAP2 (AP-2) family transcription factors
Signal Transduction: Nuclear signaling by ERBB4
Gene Ontology:
Molecular function: enzyme binding; protein binding; oxidoreductase activity; transcription coactivator activity
Biological process: cellular response to transforming growth factor beta stimulus; negative regulation of Wnt signaling pathway; positive regulation of extrinsic apoptotic signaling pathway; positive regulation of transcription by RNA polymerase II; skeletal system morphogenesis; regulation of signal transduction
Cellular component: cytoplasm; cytosol; Golgi apparatus; lysosome; microvillus; mitochondrion; nucleoplasm; nucleus; plasma membrane; RNA polymerase II transcription regulator complex
Genetic constraint (gnomAD): Loss-of-function variants: 72 observed, 47.81 expected, observed/expected ratio (o/e) 1.51, 90% interval 1.24 to 1.82. The synonymous counts are far from expectation, so gnomAD's model fits this gene poorly and the ratio says little. Missense variants: 905 observed, 543.33 expected, observed/expected ratio (o/e) 1.67, 90% interval 1.58 to 1.76. Synonymous variants: 355 observed, 207.23 expected, observed/expected ratio (o/e) 1.71, 90% interval 1.57 to 1.87.
Gene-disease validity (ClinGen):
ClinGen rates the evidence that WWOX causes each of these diseases.
genetic developmental and epileptic encephalopathy (autosomal recessive): Definitive. A complex neurodevelopmental disorder characterized by a range of developmental delays and epileptic encephalopathy phenotypes.
Homologues: Orthologues: chimpanzee WWOX (99% identical), macaque WWOX (98% identical), rabbit WWOX (96% identical), mouse Wwox (94% identical), pig WWOX (93% identical), guinea pig WWOX (93% identical), dog WWOX (82% identical), rat AABR07043897.1 (82% identical), tropical clawed frog XB1011895 (80% identical), zebrafish wwox (62% identical), Drosophila melanogaster Wwox (49% identical). Paralogues in human: RDH12 (31% identical), RDH11 (30% identical), RDH16 (17% identical), HSD17B7 (16% identical), HSD17B6 (16% identical), RDH5 (15% identical), HSD17B13 (15% identical), DHRS9 (14% identical), SDR9C7 (14% identical), HSD17B4 (14% identical), SDR16C5 (14% identical), HSD11B2 (14% identical), and 13 more.
Diseases named in the same sentence as WWOX in open-access papers:
WWOX is named in the same sentence as 177 diseases in open-access papers, as found by Europe PMC text mining. Sharing a sentence is not in itself a finding about the gene and the disease. The quoted sentences say what the papers report.
breast cancer (53 papers, 2004 to 2026). A primary or metastatic malignant neoplasm involving the breast. "In basal-like breast cancer, we found that a low WWOX/HIF1A ratio is associated with particularly aggressive disease because it promotes EMT via ZEB1 and ADAM9, facilitates ECM remodelling via MMP2 and ITGA1, and enables immune evasion via NOTCH1 and TLR4." (PMID 41007296, 2025). "In the presented work we analysed TCGA data, exploring how the WWOX/HIF1A ratio is associated with differentiation of tumour transcriptomes of breast cancer, hepatocellular carcinoma, and brain tumours." (PMID 41007296, 2025). "In the MCF7 breast cancer cell line, depletion of WWOX leads to an increase in DSBs following DNA damage induction, and the loss of the WWOX gene product results in genomic instability post-DNA damage." (PMID 41228229, 2025). "Loss or reduced expression of WWOX has been associated with breast cancer development and progression." (PMID 38499540, 2024). "In the study, we performed biological and global gene expression analysis of breast cancer cell lines in the context of differential expression of WWOX tumor suppressor gene in association with estrogen receptor response." (PMID 35290621, 2022). "As shown, all examined breast cancer cell lines show differential expression genes of TGFα-EGFR signaling which is associated with WWOX protein level." (PMID 35290621, 2022). "TGFα-EGFR signaling was found to be significantly affected in all examined breast cancer cell lines in response to estrogen and strongly associated with the level of WWOX expression, especially in ER-positive MCF7 cells." (PMID 35290621, 2022). "There are also several studies showing the association of WWOX expression with ER status of breast cancer and cancer invasiveness." (PMID 35290621, 2022). "The WW domain-containing oxidoreductase (WWOX) gene, frequently altered in breast cancer, encodes a tumor suppressor whose function is mediated through its interactions with cancer-related proteins, such as the pro-apoptotic protein p73α." (PMID 30285739, 2018). "Loss of WWOX expression in breast cancer is significantly associated with the number of metastatic axillary lymph nodes and poor survival." (PMID 30619734, 2018). "Great efforts have been made to reveal the biological functions of WWOX and identify the signaling pathways associated with its expression, not limited to breast cancer." (PMID 30211123, 2018). "The first example, WBP1 (WW domain binding protein 1), is a binding partner of WWOX tumor suppressor that is frequently mutated in breast cancer." (PMID 25749525, 2015). "Further studies have revealed that LOH is associated with a reduction in WWOX expression in gastric, esophageal, pancreatic, lung and breast cancer, as well as in glioblastoma multiforme." (PMID 25295115, 2014). "Loss of WWOX expression leads to significant upmodulation of SMAD3 transcriptional activity leading to overexpression of multiple gene targets associated with breast cancer progression." (PMID 24330518, 2013). "Since we and others observed consistent and significant loss of WWOX expression in breast cancer we focused first in the mammary gland." (PMID 22574198, 2012). "In this study, the expression of the breast cancer susceptibility gene BRCA1 and the tumor suppressor gene WWOX is detected using the immunohistochemical method in young and old female breast cancer patients." (PMID 23276146, 2012). "Moreover, WWOX-deficient breast cancer cells exhibit enhanced HR and reduced NHEJ repair, resulting in resistance to cisplatin and radiotherapy." (PMID 41228229, 2025). "Although previous studies found that WWOX expression was reduced in various cancers, our study has shown that it may be a risk factor affecting the prognosis of breast cancer." (PMID 36960071, 2023).
breast cancer (continued). "Furthermore, aberrant expression of WWOX has been shown to be associated with CSC markers in infiltrating breast cancer." (PMID 36572673, 2022). "To evaluate whether more discrete variations of VOPP1 vs. WWOX expressions could predict the risk of breast cancer metastasis with a higher efficacy, we tested the VOPP1/WWOX ratio in univariate and multivariate analyses." (PMID 30285739, 2018). "Thus, we feel it is important to understand the functions of WWOX in normal breast cells and the effects of loss of expression of this protein in breast cancer progression." (PMID 24330518, 2013). "Loss of WWOX expression has been reported in many different cancers including breast cancer." (PMID 22574198, 2012). "Interestingly, the WWOX/HIF1A ratio appears to be associated with prognosis in patients with various subtypes of breast cancer, brain tumours, and HCC, suggesting it may impact important biological processes in these cancers." (PMID 41007296, 2025). "Low expression or deletion of WWOX, as well as copy number variation, have been associated with increased invasiveness and poor prognosis in various tumors, including lung cancer, breast cancer, HCC, gastric cancer, ovarian cancer, intrahepatic cholangiocarcinoma and clear cell renal cell carcinoma." (PMID 41228229, 2025). "In addition, since we recently observed a strong association between loss of WWOX expression and estrogen and progesterone receptor (ER and PR) status in breast cancer, we also investigated any potential association between expression of sex steroid hormone receptors and WWOX in ovarian cancer." (PMID 15982416, 2005). "Not only are HIF1A and WWOX differentially expressed between malignant and benign breast cancer tissue, but this is also true for the expression of key glycolysis genes." (PMID 41007296, 2025). "Specifically, in basal-like breast cancer, we observed that low WWOX/HIF1A ratios correlate with upregulation of key proliferative pathways—including PI3K-Akt, MAPK, Ras, and ErbB signalling—which collectively drive tumour aggressiveness and rapid growth." (PMID 41007296, 2025). "The knockdown of WWOX in MCF7 breast cancer cells leads to the upregulation of HIF-1α glycolysis genes." (PMID 41228229, 2025). "Data support that WWOX inhibits excessive HIF1α transactivation, acting as a protective factor, a mechanism that is impaired in breast cancer." (PMID 41007296, 2025). "In comparison to adjacent non-neoplastic tissues, both the promoter and exon 1 regions of the WWOX gene exhibit hypermethylation in lung and breast cancers, which correlates with reduced WWOX expression." (PMID 41228229, 2025). "This study assessed the prognostic significance of the WWOX/HIF1A ratio in various cancers: breast cancer subtypes, glioblastoma multiforme, low-grade glioma, and hepatocellular carcinoma." (PMID 41007296, 2025). "In basal breast cancer cases with a high WWOX/HIF1A ratio, pathways favouring oxidative phosphorylation (Complexes I–V: NDUFA/B/C/S/V, SDHC, COX, ATP6 family) were enriched, reducing reliance on glycolysis and limiting tumour proliferation." (PMID 41007296, 2025). "We observed a similar scenario in HER2-positive breast cancer, where our data confirm that low WWOX/HIF1A ratios intensify oncogenic signalling." (PMID 41007296, 2025). "In contrast, in luminal A breast cancer subtype, our results reveal a more complex and, at times, paradoxical relationship with the WWOX/HIF1A ratio." (PMID 41007296, 2025). "In luminal B breast cancer, our data show that both WWOX and TRIM67 remain underutilized in clinical practice." (PMID 41007296, 2025). "In summary, our study revealed that WWOX and BRCA1 loss led to the development of basal-like mammary tumors and impaired DSB repair." (PMID 38499540, 2024).
breast cancer (continued). "Recent genomic studies have identified germline biallelic aberrations of WWOX in patients with multiple primary cancers including breast cancer." (PMID 38499540, 2024). "WWOX inactivation can hence contribute to the disruption of these processes, promoting tumorigenesis in breast cancer." (PMID 38499540, 2024). "In breast cancer cells, WWOX inhibits homologous recombination (HR), and thus promotes the repair of DNA double-stranded breaks (DSBs) by non-homologous end joining (NHEJ)." (PMID 37248434, 2023). "In a cross-sectional study of 185 women with breast cancer, higher neighborhood deprivation was associated with decreased methylation and gene expression of 2 tumor suppressor genes, LRIG1 and WWOX, for Black patients with breast cancer." (PMID 37930698, 2023). "Herein, we have tried to assess the relationship between the presence of estrogen receptors and the WWOX gene in breast cancer cell lines." (PMID 35290621, 2022). "Our findings showed that such TGFα-EGFR carcinogenic action can be enhanced in breast cancer with low expression of WWOX tumor suppressor gene which is supposed to be a very common event in this tumor." (PMID 35290621, 2022). "WWOX is a tumor-suppressive steroid dehydrogenase, which relationship with hormone receptors was shown both in animal models and breast cancer patients." (PMID 35290621, 2022). "Consistent with this notion, it has been reported that WWOX can inhibit the TGFβ signaling pathway in breast cancer cells by directly binding to SMAD3." (PMID 36572673, 2022). "The modulation of adhesion, invasion, and apoptotic properties in all examined breast cancer cell lines, depending on the level of WWOX tumor suppressor gene expression, as well as the treatment of estrogen, was confirmed." (PMID 35290621, 2022). "WW domain-containing oxidoreductase (WWOX) inhibits the proliferation and metastasis of breast cancer cells by inhibiting the phosphorylation of JAK2 to hinder STAT3 activation." (PMID 36230903, 2022). "WWOX knockdown in the MCF7 breast cancer cell line led to the upregulation of HIF1α glycolytic genes." (PMID 36271927, 2022). "As our experiments show, ER-positive MCF7 breast cancer cells showed increased aggressiveness when estradiol action was combined with lowered WWOX protein levels." (PMID 35290621, 2022). "Our results show that WWOX differential expression together with the effects of estrogen significantly affects gene expression profiles of model breast cancer cell lines." (PMID 35290621, 2022). "As was reported by us and others, another tyrosine receptor kinases pathway which depends on the WWOX expression gene is ERBB4 signaling in breast cancer cells." (PMID 35290621, 2022). "The lncRNA PARTICLE controls the expression of tumor suppressors MAT2A and WWOX in breast cancer and osteosarcoma respectively." (PMID 34207434, 2021). "We observed that EDA2R, MAP3K4, and WWOX exhibited reduced mRNA expression in 1,085 breast cancer tissues compared with 291 normal breast tissues." (PMID 35186006, 2021). "This pattern was confirmed in breast carcinoma, where AP-2γ nuclear translocation resulting from WWOX inactivation was observed during tumor progression." (PMID 33691672, 2021). "For example, hypermethylation of CpG islands at the WWOX promoter has been shown to transcriptionally inactivate WWOX in ovarian, pancreatic, lung, and breast cancer cell lines." (PMID 33129329, 2020). "Altogether, our results reveal WWOX, the gene product of FRA16D, as a bona fide breast cancer tumor suppressor with important functions in maintaining genome stability." (PMID 30082886, 2018). "We found that WWOX specifically co-precipitated with VOPP1 indicating that endogenous WWOX and VOPP1 were physically associated in breast cancer cells." (PMID 30285739, 2018).
breast cancer (continued). "All these observations support strongly that overexpression of VOPP1 induces breast cancer by impairing the tumor suppressive activity of WWOX." (PMID 30285739, 2018). "In this study, we defined VOPP1 as a new molecular partner and an inhibitor of the apoptotic function of WWOX in breast cancer cells." (PMID 30285739, 2018). "In breast cancer cells, VOPP1 sequestrates WWOX in lysosomes, impairs its ability to associate with p73α, and inhibits WWOX-dependent apoptosis." (PMID 30285739, 2018). "WW domain oxidoreductase (WWOX) is a tumor suppressor gene, which is altered in different types of cancer, including breast cancer." (PMID 30619734, 2018). "It was revealed that WWOX overexpression or endogenous WWOX reactivation in breast cancer cells leads to apoptotic cell death in vitro and suppression of breast tumor growth in vivo." (PMID 30619734, 2018). "Another study demonstrated that WWOX induces breast cancer cell apoptosis by triggering Smad4 transcriptional activity." (PMID 30619734, 2018). "Similar observations, were made on a breast cancer cell line, where ectopical overexpression of WWOX gene in MDA-MB-231 breast cancer cells changed cell growth in Matrigel from tumor-like to branched structures, which resembled normal mammary duct formation." (PMID 30211123, 2018). "We found that WWOX loss is associated with worse prognosis in BLBC, and that its targeted deletion in murine mammary epithelium leads to mammary tumors resembling BLBC." (PMID 30082886, 2018). "A strong positive relationship was found between WWOX expression and ER (p < 0.001) or PR (p = 0.001) by immunostaining of tissue microarrays constructed from 837 breast cancer blocks." (PMID 30211123, 2018). "Deletions within the WWOX coding sequence are observed in up to 80% of breast cancer cases, which makes it one of the most common genetic alterations in this tumor type." (PMID 30211123, 2018). "Surprisingly, contrary to animal studies, where WWOX inhibits tumorigenesis, elevated transcription of WWOX in MDA-MB-231 breast cancer cells was found to escalate migration through the basal membrane (Matrigel test), suggesting increased invasiveness." (PMID 30211123, 2018). "Surprisingly, we found that genetic alterations of WWOX were a rare event in this dataset of human patients, despite multiple evidence for WWOX protein expression reduction in clinical samples of breast cancer, and in TNBC in particular." (PMID 30082886, 2018). "In breast cancer cells, WWOX was also found to modulate the expression of glycolysis pathway genes, through hypoxia-inducible transcription factor 1α (HIF1α) regulation." (PMID 30211123, 2018). "To further determine the impact of WWOX deletion, we used CRISPR technology to knockout WWOX in a WWOX-positive breast cancer cell line." (PMID 30082886, 2018). "PARTICLE knockdown resulted in increased WWOX transcript levels in the breast cancer cell line MDA-MB-361." (PMID 28769061, 2017). "Previous studies showed that bcl-2 expression was inhibited by WWOX in breast cancer and bladder cancer, and that RUNX2 expression is up-regulated in WWOX-deficient mice." (PMID 28977834, 2017). "It is possible that WWOX inhibits the expression of these factors similarly in many cell types in addition to osteosarcoma and breast cancer cells." (PMID 28977834, 2017). "As a typical tumor suppressor, the status of WWOX expression is strongly coupled with breast cancer progression and prognosis." (PMID 28724435, 2017). "In breast cancer samples, the presence of membranous WWOX and ERBB4 strongly correlated with favourable outcome, and such coexpression seemed to have prognostic significance." (PMID 24938873, 2014).